IGHJ4 (immunoglobulin heavy joining 4)
Synonyms: JH4b
Gene: Immunoglobulin joining (J) gene on chromosome 14 (105,864,215 to 105,864,260, reverse strand). Ensembl gene ENSG00000240041.
Diseases named in the same sentence as IGHJ4 in open-access papers:
IGHJ4 is named in the same sentence as 7 diseases in open-access papers, as found by Europe PMC text mining. Sharing a sentence is not in itself a finding about the gene and the disease. The quoted sentences say what the papers report.
autoimmune disease (1 paper, 2025). A disorder resulting from loss of function or tissue destruction of an organ or multiple organs, arising from humoral or cellular immune responses of the individual to their own tissue constituents. "Interestingly, while previous studies have shown that IGHJ4 is preferentially utilized across various immune-related conditions, including autoimmune diseases, cancers, and infectious diseases, our study found a distinct pattern." (PMID 40575482, 2025).
COVID-19 (1 paper, 2023). A disease caused by infection with severe acute respiratory syndrome coronavirus 2. "Finally, we assessed a V(D)J rearrangement of heavy chain IgHV3, IGHJ4, and IGHD3/IGHD2 families in COVID-19 patients regardless of the severity of the disease." (PMID 36826040, 2023).
MALT lymphoma (1 paper, 2022). An indolent, extranodal type of non-Hodgkin lymphoma composed of small B-lymphocytes (centrocyte-like cells). "IGHV1-69, IGHJ4 and IGKV3-20 were used by the MALT lymphomas and the large RF clones that expanded after RTX." (PMID 35144926, 2022).
myeloma (1 paper, 2020). "Compared to the normal B-cell repertoire, gene selection was biased in myeloma, with significant overrepresentation of IGHV3, IGHD2 and IGHD3, as well as IGHJ4 gene groups." (PMID 32029700, 2020).
IGHJ4 also shares sentences with these, for which no sentence is quoted: cancer (1 paper); infection (1); infectious disease (1).